IL6 (interleukin 6)
Diseases named in the same sentence as IL6 in open-access papers (continued):
Sharing a sentence is not in itself a finding about the gene and the disease.
infection (continued). "Transcriptomic analysis showed that IL-6 is the most up-regulated cytokine, compatible with past transcriptomic data from infections of primary human monocyte-derived macrophages." (PMID 34280250, 2021). "Others also found that Day 1 IL-6 levels were significantly higher in patients with a complicated infection when compared to uncomplicated SAB." (PMID 33820537, 2021). "There we found that TLR2, IL6, OAT4, and CYP3A4 were significantly associated with the occurrence of infection." (PMID 33776761, 2021). "In contrast, the expression of other inflammatory cytokines TNF, IL-6, and IL-8 was increased upon infection by chronic infection isolates compared to early isolates." (PMID 33664232, 2021). "Not only IFNγ impact the BM, other cytokines that are produced by Mφ, such as IL-6, TNF and type I IFN, have been also associated with disturbances in BM precursors after infection and/or inflammation." (PMID 34987496, 2021). "IL-8 was produced at basal level and its expression was enhanced upon infection, while the two others (IL-6, and TNFα) were mostly induced by L. monocytogenes." (PMID 34367171, 2021). "Overall, the mRNA levels of inflammatory cytokines (TNFα, IL-6, and IL-10) were slightly elevated compared with what is seen in the lungs of deer mice (~2–5-fold increase) following experimental infection with SNV39." (PMID 34127676, 2021). "Initially, IL-6 was categorized as a pro-inflammatory cytokine, given its upregulation during infection." (PMID 34948868, 2021). "The cytokines are complemented by infection and inflammation related proteins such as IL6 or IL18 and TNF, the key players in infectious disease states with both beneficial and harmful, pleiotropic activities." (PMID 35145507, 2021). "Significantly higher levels of proinflammatory cytokines IL-1α, IL-1β, and IL-6 were observed in control mice during infection." (PMID 33514747, 2021). "These cells respond by releasing inflammatory cytokines such as TNF-α, IL-1β, and IL-6, aiming to eradicate the infection and maintain homeostasis." (PMID 33731173, 2021). "In the present study, the level of serum baboon IL-6 in baboons that were euthanized or died from rejection was significantly increased, and was higher than in those euthanized for infection." (PMID 34956220, 2021). "In order to explicate the difference in mortality between mice infected with S. suis strain P1/7 and S. parasuis strains at early phase of infection, we also compared their kinetics of inducing TNF-a and IL-6 production in vivo within 24 h post-infection." (PMID 34357984, 2021). "We found a marked increase in the release of the pro-inflammatory cytokines TNF-α, IL-1β, and IL-6, after infection, when compared to controls." (PMID 33669494, 2021). "The IL-6 mRNA expression level in group IV was lower in the trachea and lung compared with other groups at day 1–7 post-infection." (PMID 34988139, 2021). "The levels of serum baboon IL-6 were also significantly increased (range from 272 to 748pg/mL) in the Infection group, but were higher in the Rejection group (3291+/-1273 vs 456+/-148pg/mL, p<0.05) (right)." (PMID 34956220, 2021). "Pro-inflammatory markers regulated by PARPs such as TNF-α and IL-6 have been observed to be upregulated during infection that contribute towards the cytokine storm during infection." (PMID 34485381, 2021). "Levels of infection-related indices, such as interleukin 6 (IL-6) (35 (24.10%)), C reactive protein (CRP) (40 (19.00%)) and ESR (19 (17.00%)), were also elevated in some patients." (PMID 34697118, 2021). "The levels of serum cytokines (IL‐6, IL‐8) in the asymptomatic infection group were between the SFTS patients group and the healthy people group." (PMID 33590892, 2021). "During infection, increased IL-6 levels promote migration of neutrophils to the site of inflammation and reduce leukocyte apoptosis." (PMID 34447797, 2021).
infection (continued). "At 24 h post-infection, serum levels of IL-6, IL-17A, TNF-α, and IFN-γ were greatly reduced in IL-38-treated group, CCL2 and CXCL10 decreased at day 4, IL-1β and CCL-5 decreased on day 7 in the IL-38-treated group compared with group without IL-38 treatment." (PMID 33414457, 2021). "In response to infection by L. monocytogenes, trophoblasts produce pro-inflammatory cytokines (predominantly IL-6 and TNFα) as well as neutrophil, natural killer, and monocyte chemokines (predominantly IL8 and MIP-1α/β)." (PMID 34367171, 2021). "Cytokine IL‐6 is locally produced in response to infection or injury and delivered to other body parts by the bloodstream, activating immunological defences." (PMID 33709536, 2021). "The results showed that the ability of MS_Rv2650c to stimulate the secretion of cytokines TNF-α, IL-1β, IL-6, and IL-10 was lower than that of MS_Vec after 24 h of infection (paired t-test; P = 0.000006, P = 0.004, P = 0.01, P = 0.00002, respectively)." (PMID 35111145, 2021). "In fact, although six patients presented superimposed infection during the hospital stay, the increased levels of IL-6 at admission should be regarded as marker of severity of COVID-19 infection." (PMID 33755815, 2021). "IL-4, IL-6, IL-10, and TGF-β were associated with infection progression, while IFN-γ was correlated to tissue damage." (PMID 34276650, 2021). "Interleukin-6 is an acute phase inflammation parameter and is secreted during infection, injuries or can be also involved in cancer development and proliferation." (PMID 34208817, 2021). "Amongst critical patients, we found that the serum and plasma of those who succumbed to the infection contained significantly more IL-6 and IP-10 than control patients." (PMID 34790978, 2021). "By day 10 after infection, serum IL-6 concentrations in SCFP-fed calves declined and were similar to baseline levels." (PMID 34673945, 2021). "After 8 h post-infection, the production of pro-inflammatory cytokines and chemokines, including IL-6, IFN-γ, TNF-α, and MCP-1, was pronounced in the plasma, which is associated with the septic symptoms." (PMID 34681611, 2021). "We also show that up-regulation of Il6 expression in the BM after infection with M. avium is dependent on iNOS." (PMID 34987496, 2021). "Interleukin 6 (IL-6) is a member of the IL-6 cytokine family, secreted by many cell types upon stimulation during infection, inflammation, or cancer." (PMID 34639073, 2021). "We found that IL-1β (p < 0.0001), IL-6 (p < 0.001), and IL-2R (p < 0.0001) raised among patient specimens infected with A. fumigatus; IL-10 was slightly increased after infection (p < 0.05)." (PMID 34222495, 2021). "As IL-6 represents a keystone cytokine in infection, cancer, and inflammation and can potentially drive disease progression, it is essential to establish how IL-6 contributes to maintaining cutaneous integrity as well." (PMID 34295313, 2021). "Patients also have elevated levels of cytokines and chemokines like interleukin-6 (IL-6), interleukin-8 (IL-8), and interleukin-10 (IL-10) after infection." (PMID 34946799, 2021). "Loss of SETDB2 with coronavirus infection led to increased production of inflammatory cytokines (IL-1β, TNFα, and IL-6) in Mφs via alterations in H3K9me3 at NFkB binding sites on inflammatory gene promoters following infection." (PMID 34479991, 2021). "As previously reported in MTE4-14 cells and TECs, IL-6 expression increased during the CV-B4 infection." (PMID 33672010, 2021). "The differentiation of suppressive myeloid cells in this cell model depended on the cytokines IL-6 and IL-10, indicating a role for systemic factors in inducing myeloid dysregulation in patients with severe infections." (PMID 34103408, 2021). "The amount of soluble CXCL10, CCL5, and IL6 was increased in the supernatant of infected astrocytes at 2 dpi, but it varies depending on the isolates used for infection similarly to the results obtained by RT-qPCR." (PMID 33407600, 2021).
infection (continued). "Leukocytes fight infection and regulate immunity by secreting key immunomodulatory cytokines such as interleukin-1β (IL-1β), IL-6, IL-4, and tumor necrosis factor-α to promote tissue healing." (PMID 33846295, 2021). "The intensive care unit stay, the hemodynamic instability, the cause of death, the presence of risk factors for cardiovascular disease and the presence of ongoing infection resulted as significant determinants of IL-6 and CXCL10 donor concentrations." (PMID 33758270, 2021). "IL-6 is known to induce hypoferremia of infection and inflammation by stimulating the synthesis of hepcidin." (PMID 33995348, 2021). "iNos mRNA levels were highest 14 h after infection and decreased thereafter, whereas Tnf, Il-6 and Il-10 decreased continuously over time." (PMID 34359992, 2021). "Administration of the inhibitor significantly prolonged survival of the animals and reduced the levels of circulating IL-1β and TNF-α and partly IL-6 at 20 hours after infection." (PMID 34236052, 2021). "Overall, our gene expression data largely recapitulated previously detected gene expression following infection with Nm, including the described upregulation of nfκbiz and il6." (PMID 34863201, 2021). "As mentioned, four of these cytokines (IL-1α, IL-6, IL-8 and CXCL10) are associated with activation of the innate immune response to infection." (PMID 33657181, 2021). "Independent of the role of hepcidin, several other cytokines such as tumor necrosis factor alpha, interferon gamma, interleukin-1, and interleukin-6 also modulate iron metabolism and the iron-withholding defense during infection." (PMID 34247585, 2021). "The upregulation of inflammatory cytokines such as IL-2, IL-6, IL-8, and IL-17A correlated with higher severity of infection and more extreme symptoms such as organ injury." (PMID 34960687, 2021). "Cytokines, especially IL-6, due to severe infection and DKA, stimulate ferritin synthesis and downregulate iron export resulting in intracellular iron overload, further exacerbating the process." (PMID 33920755, 2021). "Compatible with the behavior of the MyD88 KO, TLR2 and TLR5 proved important for both IL-6 and TNFα secretion following infection with L. pneumophila." (PMID 34280250, 2021). "Interleukin (IL)-6 is the main inflammatory cytokine released by B cells during the initial stage of infection." (PMID 34040603, 2021). "In all three cases, the KDs diminished IL-6 production at 9 h after infection, and the magnitude of the effect was comparable to those tied to the TLRs." (PMID 34280250, 2021). "Next, we defined proinflammatory macrophages as cells expressing high levels of CCL2 and CCL3, chemokines involved in recruitment of adaptive and innate cells to sites of infection, and which were also characterized by the expression IL6, IL1B, and TNF." (PMID 33622974, 2021). "Proper amount of IL-6 protect individuals against pathogen infection and tissue injury, whereas excessive IL-6 production results in pathological disorders." (PMID 34766001, 2021). "In this study, the percentage of IL-6, IL-21, IL-1α, IL-17 γδT cells increased significantly after infection (p < 0.05)." (PMID 33588839, 2021). "Typically, Th1 responses are characterized by changes in TNFα, INFγ, nitric oxide, IL-1 and IL-6, which are important in promoting and maintaining proinflammatory responses during infection." (PMID 34798906, 2021). "Regarding the asymptomatic but infected donors (A and JC), JC had a different profile and exhibited higher mRNA expression of IL-6 and IL-8 compared to A and JM-3 at the same point of infection." (PMID 34669281, 2021). "IL-17 is a proinflammatory cytokine that mobilizes monocytes and neutrophils to the site of infection, and the activation of IL-17 successively activates several downstream cytokines and chemokines, including IL-1, IL-6, IL-8, IL-21, TNF-β, and MCP-1." (PMID 35054427, 2021).
infection (continued). "IL-1β induces other cytokines including IL-1β itself, IL-1RA, TNFα, IL-6, and chemokines and adhesion molecules to promote early recruitment of neutrophils and other immune cells to infection sites." (PMID 33571211, 2021). "TNF-α is secreted by macrophages, natural killer cells, endothelial cells, and fibroblasts, and induces the proinflammatory cytokines IL-1β and IL-6, which are involved in innate immunity in the early stages of infection." (PMID 34884507, 2021). "In support of this idea, the number of neutrophils in Il-6 knockout (IL-6 KO) mice at 3 h post-infection appears to be lower than that in WT mice." (PMID 34040603, 2021). "Of particular importance are the Pa-induced chemokine CXCL8, which is instrumental in neutrophil migration to the site of infection, and the cytokine IL-6, which is involved in the release of acute phase proteins and immune cell differentiation." (PMID 33524056, 2021). "This regulation is required to limit the levels of TNF-α, IL-1β and IL-6 in the skin after infection." (PMID 34006861, 2021). "Real-time quantitative PCR was used to detect the mRNA relative expression of pro-inflammatory cytokines, including TNF-α, IL-1β, IL-4, and IL-6 in the supernatant of endothelial cells 48 h after infection with influenza virus." (PMID 34414033, 2021). "CH223191, on the other hand, increased the synthesis of il-6 but reduced il-17 and il-22 mRNA at both post-infection periods, but tgf-β only at 96 hours after infection." (PMID 33936043, 2021). "Cruz Hernandez and colleagues (2016) observed significantly higher IL-6 and TNFα expression in DENV-2 than DENV-1 in primary infection; our observation is similar, where IL-6 and TNFα were significantly elevated in DENV-2." (PMID 34447698, 2021). "We found that in vivo Mφs isolated from DIO mice following MHV-A59 infection demonstrated decreased H3K9me3 at NFkB binding sites on the promoter(s) IL-1β, TNFα, and IL-6 compared to infected ND Mφs." (PMID 34479991, 2021). "In dengue infection, the increase of cytokines such as IL-6 and IL-1 beta could cause the activation of monocytes, platelets and coagulation enzymes, hence promoting the localization and interaction of monocytes–platelets at the site of infection, such as endothelial cells." (PMID 33919457, 2021). "It was found that Rufomycin 4–7 treatment significantly decreased the Mabs-R-induced gene expression of various proinflammatory cytokines and chemokines (Tnfa, Il1b, Il6, Cxcl5, Ccl2, and Ccl4) in BMDMs at 6 h post-infection (hpi)." (PMID 34447358, 2021). "As shown in our study, despite there was some correlation with SpO2, a ratio of PaO2/FiO2, or with CRP, the IL-6 level varies significantly during the infection and has independent meaning, which leaves space to optimizing patient selection." (PMID 33679753, 2021). "Compared to the Cal[NS1_high-PAX_low] virus, infection with Cal[NS1_high-PAX_high] induced more IL-6 and IFN-γ, even though it grew to a similar level and expresses shutoff active NS1." (PMID 34200539, 2021). "Upon infection with HBPUB10134a, AGMs exhibited 100-fold increase in IL-1 receptor antagonist (IL-1RA) and IL-6 at day 5 PI." (PMID 33571211, 2021). "They found that P2X7R was involved in dendritic cell infiltration to the site of infection, promoting TNF-α and IL-6 production in IECs, and promoting specific T cell responses during infection." (PMID 34987401, 2021). "ELISAs on cell supernatants revealed that LESB65 infection induced secretion of the pro-inflammatory cytokine IL-6 and chemokine IL-8 by HBE cells." (PMID 33777834, 2021). "Both IL-21 and IL-6 are important for generating Tfh CD4+ T cells that are selected for during LCMV Cl 13 infection." (PMID 34696381, 2021). "Among serum molecules identified in non-neurological and neurological diseases in the acute phase of the infection, 12 (IL-1β, IL-6, TNF, IL-2, IL-7, IL-17A, IL-15, IFN-α, IL-5, IL-13, IL10, and GM-CSF) were shared by both networks." (PMID 33776990, 2021).
infection (continued). "IL-6, produced rapidly in response to infection and tissue damage, promotes host defense by stimulating the acute phase responses or immune response." (PMID 34578457, 2021). "In the early stages of the infection, a group of cytokines and pro-inflammatory chemokines are expressed including interleukin-1β (IL-1β), IL-2, IL-6, interleukin-8 (IL-8), both IFN-α/β, tumor necrosis factor (TNFα), CCL, CCL3, CCL5, CCL2, and IP-10." (PMID 34220861, 2021). "In conclusion, infection of hamsters with G. lamblia lowered NO production, while increasing IL-6, IFN-γ, and TNF-α." (PMID 33919165, 2021). "Instead, the infected airway epithelia produce IL-6 and other pro-inflammatory cytokines, attracting monocytes and cytotoxic T cells to the infection site to recognize and to destroy the infected cells." (PMID 34001244, 2021). "Infection with increasing multiplicity of infection (MOI) of P. gingivalis resulted in a dose-dependent increase in IL-6 and IL-8 production by PHGFs." (PMID 34031466, 2021). "Microglia and macrophages from susceptible SJL mice produce higher levels of IL-6 and IL-1 after TMEV infection compared to those cells from either B6, B6.S, or B10.S." (PMID 34067536, 2021). "Patients with multiple infections of HPV had higher levels of IL-6 in their ECCs than those with a single infection." (PMID 33750983, 2021). "Most surprisingly, deletion of atl, clfA, and sasC resulted in increased IL-6 production compared to WT infection." (PMID 34484165, 2021). "A pronounced innate immune response to infection followed the peak of viral replication, evidenced by induction of cytokines (IL‐6, TNF), chemokines (CCL2, CCL5) and type I and III IFNs (IFNβ, IFNλ1/3) measured by RT–qPCR (and EV2D–F)." (PMID 34101213, 2021). "We depicted the IL-6 kinetics throughout the infection based on the onset of symptoms and the admission day." (PMID 33679753, 2021). "We have also described herein an upregulation of local interleukin-6 transcription at the mRNA level within the pulmonary lesions at the early time points of infection in both species." (PMID 33627662, 2021). "C57BL/6 mice infected with the hypervirulent C. neoformans H99 strain showed lower levels of IFN-γ after 14 days of infection, as well as higher levels of IL-17, IL-4 and IL-6 in comparison to uninfected C57BL/6 mice." (PMID 33446850, 2021). "Infection with SARS-CoV-2 virus causes the body’s immune response in which pro-inflammatory cytokines such as TNF-α, IL-6, IL-1β, IL-2 and IFN-γ are secreted." (PMID 34575258, 2021). "Only 4 genes overlapped both time points that also increased expression across MOIs (CXCL1, CXCL2, CXCL8 and IL6), indicating their importance as immune mediators against infection." (PMID 34001998, 2021). "When infection and inflammation occur, IL-6 is produced by monocytes and macrophages stimulated by Toll-like receptors (e.g., TLR 4) and its level rapidly increases, the magnitude of the increase reflects the severity of the disease." (PMID 34210334, 2021). "A comparison of these hematological parameters in the mild and severe infection groups showed significant differences primarily in IL-6 and CRP levels, as well as coagulation function-related indicators (fibrinogen, d-dimer and time-to-thromboplastin)." (PMID 33550983, 2021). "The expression level of S100B proteins increases in response to factors upregulated during infections such as TNFα, IL-1β, IL-6, and IL-8, also reported to be increased in prenatal infection models." (PMID 34741005, 2021). "The levels of IL‐6 and IL‐8 in the asymptomatic infection group were found between the SFTS patients group and the healthy people group." (PMID 33590892, 2021). "The IL-6 mRNA expression in group II was lower (p < 0.05) compared with levels in group I at day 5 post-infection." (PMID 34988139, 2021). "TNF, IL-1β, and IL-6, which are pro-inflammatory cytokines and released as the initial response to injury or infection." (PMID 34590796, 2021).